CRP (C-reactive protein)
Diseases named in the same sentence as CRP in open-access papers (continued):
Sharing a sentence is not in itself a finding about the gene and the disease.
diabetes (continued). "A history of hypertension, diabetes mellitus, and elevated creatinine and C-reactive protein (CRP) were correlated with clinical worsening." (PMID 30034558, 2018). "Regression models were adjusted for age, sex, race, alcohol use, smoking status, serum c-reactive protein, red blood cell folate, diabetes mellitus, glomerular filtration rate, body mass index, and hypertension." (PMID 30546973, 2018). "This study aimed to investigate the effects of liraglutide versus metformin on islet beta-cell function, metabolic products of oxidative stress and C-reactive protein (CRP) in young patients with recent onset type 2 diabetes mellitus." (PMID 30564288, 2018). "Several studies have demonstrated that initial elevated levels circulating IL-6, plasminogen activator inhibitor-1 (PAI-1), C-reactive protein (CRP) and fibrinogen, are associated with the manifestation of diabetes." (PMID 30443223, 2018). "We analyzed only several major risk factors for atherosclerosis before and after KT: hypertension, dyslipidemia, smoking, diabetes, age, inflammation, and CRP levels." (PMID 29619867, 2018). "Anthropometrics, blood pressure, serum-lipids and high-sensitivity C-reactive protein (hs-CRP) were collected and supplemented with data from the patients’ medical records and from the Swedish National Diabetes Registry." (PMID 29785272, 2018). "KT-ratio, log-transformed CRP, group, observed bacterial species, physical activity, diabetes treatment (insulin, oral), mode of HIV transmission (MSM, others), and Framingham 10 year CVD score were included in the multivariate model." (PMID 29712976, 2018). "A 66-year-old woman with a history of type 2 diabetes mellitus presented with elevated serum C-reactive protein (CRP) (6.15 mg/dL, normal range <0.35 mg/dL) at a regular checkup without any symptoms in June 2017." (PMID 29851832, 2018). "As a biomarker of inflammation, C-reactive protein (CRP) has attracted much attention due to its role in the incidence of type 2 diabetes mellitus (T2DM)." (PMID 30619477, 2018). "A very significantrelation to diabetes (p = 0.001), CRP(p = 0.005), and HDL(p = 0.007) was also found." (PMID 29257712, 2018). "Of study sample, there were 64.9% men, 38.2% diabetes, 48.2% hypertension, and 29.8% cardiovascular diseases, 28.5% with an elevated level of hs-CRP, 54.5% elevated body fat mass." (PMID 30231860, 2018). "After further adjustment for CRP, the β value of the category defined by non diabetes and overweight/obesity reverted to non statistical significance (p = 0.06)." (PMID 28946871, 2017). "In patients with diabetes, the predictive value of CRP for cardiovascular disease is a more debated issue." (PMID 28435446, 2017). "Age, diabetes mellitus, CAD, CKD, statin medication, C-reactive protein levels, and the serum concentration of the two Tn-C variants were entered into the analysis as independent variables." (PMID 29117120, 2017). "We identified ten predictors including sex, diabetes mellitus, lactate dehydrogenase level, C-reactive protein, years since drinking, chronic kidney disease (CKD), stage of CKD, stroke, acute myocardial infarction, and systolic blood pressure." (PMID 29088847, 2017). "The elevated levels of inflammatory markers, including C-reactive protein (CRP), tumor necrosis factor alpha (TNF-α), and interleukin 6 (IL6) are supposed to be associated with type 2 diabetes mellitus (T2DM)." (PMID 28716139, 2017). "Even in our study a strong positive correlation was found between NLR and CRP in patients with worst diabetes control." (PMID 29492060, 2017). "Diabetes is thus a proinflammatory state characterized by increased C-reactive protein (CRP), proinflammatory cytokines, and monocyte activation." (PMID 29435463, 2017). "In contrast, SED-time was positively associated with age, diabetes duration, HbA1c, FPG, insulin, HOMA-IR, BMI, fat mass, waist circumference, triglycerides, systolic BP, hs-CRP, ACR, UKPDS risk scores, and physical fitness measures." (PMID 28291838, 2017).
diabetes (continued). "CRP level was positively correlated with diabetes prevalence and levels of fasting and 2-hour glucose (each P < 0.008)." (PMID 28801571, 2017). "Similar to the effects that periodontal therapy has on CRP levels, the lipid profiles show greater improvement in periodontitis patients with co-morbidities, e.g. hyperlipidemia, diabetes." (PMID 28190975, 2017). "A strongly increased risk of both pre-diabetes [OR (95% CI): 2.02 (1.09, 3.75)] and T2DM [OR (95% CI): 8.10 (2.74, 23.97)] was found in subjects with CRP levels ≥1 mg/dl." (PMID 28716139, 2017). "Several risk factors of microvascular complications have been reported in adults with T2DM, such as duration of diabetes, age, blood pressure, fasting plasma glucose, urinary albumin excretion levels, and elevated C-Reactive Protein levels." (PMID 28854950, 2017). "The present study was designed to assess relationship between NLR and glycemic control which was done by comparing NLR with HbA1c in terms of excellent, poor and worst diabetes control and compare them with CRP which is the most studied inflammatory markers." (PMID 29492060, 2017). "CRP has also been intensively studied and meta-analysis for the relationship of CRP with hypertension, cardiovascular disease, and diabetes mellitus suggested its role in mediating these chronic diseases." (PMID 28115972, 2017). "Concentration of hs-cTnT correlated positively with age, male sex, body mass index, blood pressure, NT-proBNP, CRP, history of diabetes mellitus, and history of hypertension." (PMID 28750699, 2017). "During pre-diabetes, myocardia are exposed to a variety of risk factors such as elevated levels of FFA and inflammatory factors, TNF-α, IL-1β, and CRP." (PMID 28304381, 2017). "Concentrations of plasma fibrinogen, PAI-1, and CRP at Visit 2 by participant characteristics and diabetes status at baseline in Strong Heart Study main cohort participants." (PMID 28771557, 2017). "Whilst women with depressive symptoms had significantly higher risk factors associated with diabetes (central obesity levels, IR, leptin and TNF-α), depression in men was associated with higher levels of CRP which potentially suggests an increased risk of CVD." (PMID 29190710, 2017). "Various inflammatory markers are associated with progression from normoglycemia to pre-diabetes (IL13, EN-RAGE, CRP), T2D (IL13, IL17, CRP) or insulin therapy start (IL13)." (PMID 28258520, 2017). "There were no clinically significant differences in age, gender and traditional cardiovascular risk factors between the two groups, except history of smoking (52% in low CRP group vs. 78% in high CRP group, p = 0.02) and diabetes (18 vs. 39%, p = 0.048)." (PMID 29376057, 2017). "The two groups were similar regarding age, diabetes mellitus, C-reactive protein, diuresis and renal clearances, but serum albumin was significantly higher in included patients (p < 0.001)." (PMID 28859606, 2017). "In the research of specific salivary biomarkers with clinical potential for the assessment of AMI, C-reactive protein, sCD40L and CK-MB, as well as creatinine phosphokinase, TnT, and TnI resulted useful diabetes." (PMID 28512552, 2017). "Prior studies of inflammation-related markers and diabetes have measured a limited number of inflammatory markers, primarily C-reactive protein (CRP) and interleukin 6 (IL-6) and, more recently, anti-inflammatory cytokines." (PMID 28753646, 2017). "The impact of C-reactive protein in the development of type 2 diabetes mellitus highlights the importance of an inflammatory process in the diabetes pathogenesis." (PMID 28403353, 2017). "Lp-PLA2 was associated with risk of ACS in young patients when adjusted for traditional risk factors, including age, sex, diabetes, hypertension, smoking, TC, LDL-C, triglyceride and hs-CRP (OR = 1.98, 95%CI = 1.10–3.56)." (PMID 29170433, 2017). "Diabetes mellitus, increased urea, and low C-reactive protein independently predict raise in pancreatic enzyme." (PMID 28725436, 2017).
diabetes (continued). "A multivariate analysis showed that high level of NLR was independent predictor of worst diabetes control (Group C)(OR: 1.809, 95% CI: 1.459-2.401) along with fasting blood sugar (OR: 0.938, 95% CI: 0.995-0.982) and CRP (OR:1.020, 95% CI: 1.003-1.028)." (PMID 29492060, 2017). "We observed a significant trend across the quartiles for age, body-mass-index (BMI), prevalence of diabetes mellitus, fasting glucose, hemoglobin A1c (HbA1c), and C-reactive protein concentrations." (PMID 28629132, 2017). "When baseline characteristics were compared between patients who did or did not respond to oral iron by week 4, there were no marked differences in age, gender, renal function (as assessed by eGFR), presence of diabetes or hypertension, or CRP level." (PMID 29092739, 2017). "A few cross-sectional studies have been conducted in Chinese population, and suggest that CRP is positively related to prediabetes (including hyperglycemia and metabolic syndrome) and prevalent diabetes." (PMID 28178951, 2017). "We set Cat-S as the dependent variable and added independent variables as follows: eGFR, gender, age, BMI, total serum protein, serum CRP and prevalence of diabetes mellitus, arterial hypertension, vascular disease and tumor disease." (PMID 28240259, 2017). "Geometric mean ratios (95% confidence interval) of baseline fibrinogen, Visit 2 PAI-1, and Visit 2 CRP by baseline urine arsenic concentrations by diabetes status in the Strong Heart Study main cohort." (PMID 28771557, 2017). "NLR were found independent predictor of worst diabetes control (OR: 1.809, 95% CI: 1.459-2.401) along with fasting blood sugar (OR: 0.938, 95% CI: 0.995-0.982) and CRP (OR: 1.020, 95% CI: 1.003-1.028)." (PMID 29492060, 2017). "GH deficiency contributes to visceral obesity, leading to insulin resistance and dyslipidemia (especially high LDL), diabetes mellitus and chronic inflammation (specifically increased C-reactive protein)." (PMID 28196799, 2017). "Other studies have shown similar changes in persons with diabetes when matched for BMI and CRP levels." (PMID 28841871, 2017). "Age, CVD history, diabetes, hemoglobin, albumin and C-reactive protein were found as common predictors in both our studies." (PMID 29066841, 2017). "Correspondingly, inflammatory markers such as C-reactive protein are increased in patients with diabetes and in patients with arterial hypertension and do also predict the development of these diseases." (PMID 28464794, 2017). "The observation that serum HSPA/HSP70 levels are enhanced in patients with DM and correlate with C reactive protein (CRP) levels suggests that diabetes-related insults can enhance exposure/release of HSPA/HSP70." (PMID 29240668, 2017). "Thus, the slight elevation of CRP levels associated with an increased risk of cardiovascular disease is probably due to reduced perfusion of skeletal muscle caused by elevated blood viscosity, hypertension, and diabetes, all of which are risk factors for atherothrombosis." (PMID 29435395, 2017). "Neutrophil assay results were summarized for the following variables with all cohorts pooled: fasting glucose (mg/dL); HbA1c (%); BMI (kg/m2); smoking; age; sex; CRP (mg/L); statin use; use of diabetes medication, and duration of diabetic history (days)." (PMID 29026443, 2017). "Patients with AVD progression were older, with more prevalence of diabetes, higher levels of c-Reactive Protein and lower levels of 25-hydroxy-vitamin D." (PMID 29095847, 2017). "A univariate Cox regression analysis showed that age, diabetes mellitus, history of cardiovascular disease, low IGF-1, high CRP, high glucose, low LDL-cholesterol, J-DOPPS risk score, ARO risk score and high FGF21 were predictive for the all-cause mortality." (PMID 28582462, 2017). "The ameliorative effect of simvastatin on diabetes-associated inflammation was explored via determination of serum TNF-α and CRP levels and cardiac NF-κB expression." (PMID 29138670, 2017).
diabetes (continued). "The proportion of patients with hypertension, diabetes, or high cholesterol increased with the increase of quartile grade of hs-CRP concentrations (p < 0.001)." (PMID 27589783, 2016). "Diastolic BP, hs-CRP, as well as prevalent treated diabetes were similar in both genders (all p ≥ 0.129)." (PMID 27271659, 2016). "More recent study reported that the cut-off CRP level in people with diabetes for the diagnosis of osteomyelitis is 14 mg/L with a sensitivity and specificity of 85% and 83%." (PMID 28044140, 2016). "We previously reported the lost correlation between CRP and leptin in patients with type 2 diabetes mellitus, in which inflammation is considered to be a cornerstone of the disease." (PMID 27981248, 2016). "Those with low BMI had lower levels of atherogenic lipids, blood glucose, CRP, lower blood pressure and eGFR, and made up a lower proportion with diabetes." (PMID 27003294, 2016). "In the patients of the CALCITOP study 1,25(OH)2D was also inversely interrelated with EuroScore, diabetes and CRP values." (PMID 27355377, 2016). "Multivariate logistic regression identified C-reactive protein (CRP) over 150 mg/l, age over 65 years, diabetes, gangrene of the gallbladder and an abscess as risk factors for conversion." (PMID 27891173, 2016). "A correlation was observed between hs-CRP and the incidence of diabetes (highest quartile vs first quartile; HR, 1.7; 95% CI, 1.3–2.4), and the association was similar across all the ethnic groups." (PMID 27166776, 2016). "After adjusting for age, gender, BMI, hypertension, diabetes, hyperlipidaemia, current smoking status and hs-CRP, only Hcy >19.3μmol/L remained as an indicator of asymptomatic CAS (multivariate-adjusted OR 1.53, 95%CI 1.05–2.23; p-value for trend = 0.0265)." (PMID 27869211, 2016). "Compared with subjects with sustained low/moderate hs-CRP, those with increased or sustained high hs-CRP had increased risks of diabetes, coronary heart disease, ischemic stroke, heart failure and mortality." (PMID 27166776, 2016). "In the Diabetes Heart Study 26, baseline hs-CRP levels were measured in 846 subjects with type 2 diabetes who were followed-up for a mean (standard deviation [SD]) of 7.3 (2.1) years." (PMID 27166776, 2016). "It is previously shown that leptin and CRP are correlated in healthy individuals, and we reported the lost correlation between CRP and leptin in type 2 diabetes mellitus." (PMID 27981248, 2016). "Changes in CRP positively correlated with changes in HbA1c (r = 0.52, p = 0.001) which remained significant after adjusting for age, years with diabetes, and baseline weight." (PMID 27187457, 2016). "Before and during falciparum malaria, diabetes patients exhibited higher (P < 0.05) levels of CRP and peroxides than controls but TAP and BAI were comparable (P > 0.05) between the two groups." (PMID 27298824, 2016). "The median baseline CRP levels for ALPHA 18 and BETA 19 were ≤1.90 mg/L among the four intervention groups, below the 3.0 mg/L threshold considered high risk for diabetes and cardiovascular disease." (PMID 27485297, 2016). "Proportion of males, number of smokers, incidence of diabetes, heart rate, fasting blood glucose, and hs-CRP were higher in ACS group as compared to those in the control group." (PMID 27642596, 2016). "Nevertheless, a predictive value for the eQB rate with respect to the serum cTnT was detected in the present study for the ED group among other well-known cTnT determinants, including dialysis vintage, age, diabetes, serum phosphate, or serum CRP." (PMID 26603871, 2016). "Biomarkers in serum and plasma like proinflammatory cytokines, adhesion molecules, and acute-phase reactants such as C-reactive protein (CRP) are related to increased risk of cardiovascular events and diabetes-associated vascular impairment." (PMID 27240397, 2016).
diabetes (continued). "We found that old age, diabetes duration, percentage of antihypertensive medication use, antiplatelet agent use, and log hs-CRP level were significantly higher in patients with positive CUS findings." (PMID 27842497, 2016). "In this line, we demonstrated an independent association of eCAT volume with the presence and severity of CAD after the adjustment for age, diabetes mellitus, hyperlipidemia, body-mass-index (BMI), hs-CRP and hs-TnT." (PMID 27187590, 2016). "The results of our studies demonstrated that the concentration of CRP was significantly higher only in patients with diabetes suffering from PAD." (PMID 27834825, 2016). "The results showed similar sex predominance, stroke severity, stroke etiology, atrial fibrillation, functional outcome, and mortality and highlight differences for the prevalence of diabetes, smoking history, and elevated baseline C-reactive protein." (PMID 26792363, 2016). "Some inflammatory markers show different relationships with PAD in the context of disease, as is the case with C-reactive protein (CRP) and diabetes." (PMID 27938334, 2016). "Risk factors for cardiovascular disease with a pro-inflammatory component include LDL cholesterol, smoking, elevated blood sugar, hypertension, diabetes, infections, oxidant damage, interleukin-6 (IL-6) and C-reactive protein (CRP)." (PMID 27070643, 2016). "We corroborate the reported independent associations between higher on-admission fibrinogen levels and older age, higher C-reactive protein, diabetes and history of cardiovascular disease in acute ischemic stroke patients." (PMID 27576312, 2016). "We demonstrate the use of the procedure with an illustrative example involving C-reactive protein (CRP) levels and diabetes using data from the 2009–2010 National Health and Nutrition Examination Surveys (NHANES)." (PMID 27034909, 2016). "Clinically, CRP has emerged as a leading inflammatory biomarker for CVD and, thus, has been of interest to researchers studying the role of n-3 PUFAs in diabetes complications, a key CVD risk factor." (PMID 27544079, 2016). "Elevated levels of plasma CRP have been reported to enhance the development of diabetes by interacting with cytokines (IL-6 and TNF-α) in stimulating the acute phase inflammatory response." (PMID 27379252, 2016). "After adjusting for the full model (age, gender, body mass index [BMI], hypertension, diabetes, erythrocyte sedimentation rate [ESR], c-reactive protein [CRP]), sST2 was still significantly associated with higher Ct." (PMID 27554830, 2016). "Elevated markers of inflammation such as C-reactive protein or interleukin-6 have been detected in children and adults with diabetes, supporting the notion that diabetes represents a condition of chronic inflammation." (PMID 26911143, 2016). "CpGs that were significantly associated with higher BMI, fasting glucose, fasting insulin, risk of diabetes, triglycerides, and risk of CHD were also associated with higher CRP levels." (PMID 27955697, 2016). "In the JHS cohort, those who eventually developed diabetes have been shown to have higher C-reactive protein levels at baseline." (PMID 27727289, 2016). "At baseline, respondents with diabetes exhibited higher (P < 0.05) levels of CRP, peroxides, BMI, and WC but lower WHR and comparable (P > 0.05) level of TAP and BAI than their nondiabetic counterpart." (PMID 27298824, 2016). "It was shown that TC, TG, LDL, and CRP were higher in the diabetes group than those in the normal group, with HDL lower in the diabetes group (p < 0.001)." (PMID 27213415, 2016). "Suppose we wished to test for differences in the distribution of CRP between groups based on diabetes status determined by plasma fasting glucose (PFG)." (PMID 27034909, 2016). "In the British population of the Whitehall II study, baseline hs-CRP levels were predictive of diabetes." (PMID 27166776, 2016).